ADGRG7 (adhesion G protein-coupled receptor G7)
Description:
Orphan receptor.
Synonyms: GPR128; FLJ14454
Tractability: Antibody: UniProt predicts a signal peptide or a membrane-spanning region; its Gene Ontology location is reachable by antibodies, with medium confidence; the Human Protein Atlas places it where antibodies can reach.
Gene: Protein-coding gene on chromosome 3 (100,609,601 to 100,695,479, forward strand). Ensembl gene ENSG00000144820.
Subcellular location: Membrane
Subcellular location (Human Protein Atlas): Plasma membrane
Gene Ontology:
Molecular function: protein binding; G protein-coupled receptor activity; transmembrane signaling receptor activity
Biological process: G protein-coupled receptor signaling pathway; cell surface receptor signaling pathway
Cellular component: membrane; plasma membrane
Genetic constraint (gnomAD): Loss-of-function variants: 47 observed, 50.18 expected, observed/expected ratio (o/e) 0.94, 90% interval 0.74 to 1.19. The upper end of that interval is the gene's LOEUF score, 1.19, which puts it in group 5 of 6, group 1 being the genes least tolerant of losing a copy. Missense variants: 627 observed, 681.63 expected, observed/expected ratio (o/e) 0.92, 90% interval 0.86 to 0.98. Synonymous variants: 267 observed, 255.9 expected, observed/expected ratio (o/e) 1.04, 90% interval 0.94 to 1.15.
Homologues: Orthologues: chimpanzee ADGRG7 (99% identical), macaque ADGRG7 (91% identical), pig ADGRG7 (76% identical), rabbit ADGRG7 (75% identical), rat Adgrg7 (70% identical), mouse Adgrg7 (69% identical), guinea pig ADGRG7 (51% identical), dog ADGRG7 (49% identical), zebrafish adgrg7.2 (14% identical), zebrafish adgrg7.1 (7% identical). Paralogues in human: ADGRG6 (19% identical), ADGRL3 (19% identical), ADGRF3 (18% identical), ADGRF5 (18% identical), ADGRG4 (18% identical), ADGRB1 (17% identical), ADGRB2 (17% identical), ADGRL1 (17% identical), ADGRL2 (17% identical), ADGRF4 (17% identical), ADGRF1 (17% identical), ADGRG2 (16% identical), and 30 more.
Diseases named in the same sentence as ADGRG7 in open-access papers:
ADGRG7 is named in the same sentence as 22 diseases in open-access papers, as found by Europe PMC text mining. Sharing a sentence is not in itself a finding about the gene and the disease. The quoted sentences say what the papers report.
breast carcinoma (2 papers, 2014 to 2022). "DEGs Bcl3, ADGRG7, FABP4, IRF4, their regulating miRNAs and TFs have strong impact on proliferation and metastasis of breast cancer in bone tissues." (PMID 35388653, 2022).
endometriosis (2 papers, 2024 to 2025). The growth of functional endometrial tissue in anatomic sites outside the uterine body. "This is the first genomic analysis of sisters with endometriosis to identify a rare CNV gain involving ADGRG7 and TGF candidate genes." (PMID 38765507, 2024). "The rare CNV gain involving ADGRG7 and TFG genes in this family provides a new candidate genetic marker for future investigations involving familial endometriosis." (PMID 38765507, 2024).
viral infections (2 papers, 2023 to 2024). "For the first time, we have identified new CRS-related genes such as ADGRG7, probably reflecting cellular-adhesion elements, LACRT, IBSP, MEPE, and IFITM5, probable antimicrobial genes with a potential role in viral infections." (PMID 36982612, 2023). "In light of reanalysed RNAseq data and our findings, we believe that further research into the role of ADGRD1/GPR133 (but likely not ADGRG7/GPR128) in viral infections is warranted." (PMID 38786015, 2024).
adolescent idiopathic scoliosis (1 paper, 2019). A scoliosis with no known cause arising in adolescent. "The functional involvement of this receptor was linked with different physiological process such as reduced body weight, gastrointestinal function and recently, a gene variant in ADGRG7 was observed in patients with adolescent idiopathic scoliosis." (PMID 30598481, 2019). "We found that ADGRG7 expression was upregulated in response to estrogen (E2) in adolescent idiopathic scoliosis (AIS) cells." (PMID 30598481, 2019).
ischaemic stroke (1 paper, 2023). "Random forest analysis suggested a panel of differentially expressed genes (ADGRG7 and miRNAs 96, 532, 6766, 6798 and 6804) as potential ischaemic stroke biomarkers, although modelling analyses demonstrated that these genes had poor diagnostic performance." (PMID 38007520, 2023). "ADGRG7 is an oestrogen-responsive gene implicated in the development and progression of multiple cancer types, but has not been specifically associated with ischaemic stroke." (PMID 38007520, 2023).
medulloblastoma (1 paper, 2022). A malignant, invasive embryonal neoplasm arising from the cerebellum. "Additional selected linear fusions in medulloblastoma that cannot be interpreted via read-through transcription are the TFG--ADGRG7 and the PVT1--CASC8." (PMID 35804907, 2022). "In fact, the 2 medulloblastoma samples expressing the TFG--ADGRG7 circular fusion also express the TFG--ADGRG7 linear fusion." (PMID 35804907, 2022).
periodontitis (1 paper, 2025). An acute or chronic inflammatory process that affects the tissues that surround and support the teeth. "ADGRG7 (Log2FC=-9.7) and Chromosome 6 Open Reading Frame 15 (C6orf15) (Log2FC=-8.2) showed the strongest downregulation in periodontitis." (PMID 41124422, 2025).
tumor (6 papers, 2017 to 2024). "Tumor microenvironment related genes ADGRG7, CSN3, CST8, KRT81, MUC7, MYH6, and SEZ6 are valuable predictors for HNSCC patient survival." (PMID 33530209, 2021). "Functional analysis of ADGRG7, CST8, and SEZ6 in tumor biology has not been reported." (PMID 33530209, 2021). "The role of ADGRG7 and CST8 in tumor biology has not been reported." (PMID 33530209, 2021).
infection (1 paper, 2024). The state of being infected such as from the introduction of a foreign agent such as serum, vaccine, antigenic substance or organism. "Nevertheless, examination of the GSE252056 dataset revealed 3.2-fold upregulation of ADGRG7 24 h post infection and striking 18.7-fold downregulation after 48 h of SARS-CoV-2 infection." (PMID 38786015, 2024). "The increase in mRNA expression of ADGRD1/GPR133 and ADGRG7/GPR128 after 24/48 h increased more than three times compared to the mRNA expression change 12 h after infection." (PMID 38786015, 2024). "In Calu-3 cells, the relative mRNA expression upon infection with infectious SARS-CoV-2 exhibited a pronounced increase in the cases of ADGRD1/GPR133 and ADGRG7/GPR128, a small increase in the case of ADGRB3/BAI3 and a negligible change in that of ADGRV1/GPR98 mRNA levels after 24 and 48 h." (PMID 38786015, 2024). "In Caco-2 cells, no increase in mRNA expression of ADGRB3/BAI3, ADGRG7/GPR128 and ADGRV1/GPR98 was detected even 48 h after infection, thus confirming our results after 12 h post infection." (PMID 38786015, 2024).
skeletal dysplasia (1 paper, 2020). Any Mendelian diseases that affects growth and development of the skeleton. "Upregulated expression of the ADGRG7 gene (GPR128) is associated with another rare skeletal dysplasia: Fibrogenesis Imperfecta Ossium." (PMID 33228694, 2020).
ADGRG7 also shares sentences with these, for which no sentence is quoted: cancer (7 papers); clear cell renal carcinoma (1); congenital heart defects (1); gastrointestinal tumors (1); genetic diseases (1); liver cancer (1); lung adenocarcinoma (1); melanoma (1); neurodevelopmental disorder (1); psoriasis (1); Sézary syndrome (1); Tinnitus (1).